FTO (FTO alpha-ketoglutarate dependent dioxygenase)
Diseases named in the same sentence as FTO in open-access papers (continued):
Sharing a sentence is not in itself a finding about the gene and the disease.
Obesity (continued). "This research consists of 18 studies that looked at the risk of obesity due to genetics in the FTO rs9939609 gene variant in various ethnicities in Asia." (PMID 39981080, 2025). "The FTO gene, known for its association with obesity and metabolic syndrome, showed a minor allele frequency of SNP rs1421085 28.3% in the Kazakh population." (PMID 41234028, 2025). "FTO harbors the genetic variant rs9939609-A, which has been primarily associated with higher BMI and obesity." (PMID 41301409, 2025). "In Indonesia, the variant most studied among various ethnicities is the FTO rs9939609 variant with allele A and genotype AA as risk factors for obesity." (PMID 39981080, 2025). "This research has proven that certain genotypes variant FTO rs9939609 have a different risk of obesity between one genotype and another." (PMID 39981080, 2025). "The fat mass- and obesity-associated gene (FTO) is critically involved in the regulation of postnatal growth." (PMID 40429638, 2025). "Fat mass and obesity-associated protein (FTO) was initially characterized as a gene implicated in obesity and energy metabolism and was then identified as the RNA m6A demethylase." (PMID 39773744, 2025). "The fat mass and obesity-associated (FTO) gene has lately emerged as one of the most widely studied genes linked to body mass." (PMID 40630163, 2025). "In this study, we aimed to gain insight into the molecular mechanisms underlying the obesity-associated enhancer in the FTO locus by uncovering genes that are under direct transcriptional control of IRX3 in developing preadipocytes." (PMID 40769964, 2025). "In that year, three independent studies simultaneously reported a statistical association of genetic variants within the gene FTO with BMI and obesity in children and adults." (PMID 41082226, 2025). "FTO is a known key gene associated with obesity in humans through the GWAS study and fat deposition on various animals, including pigs and cattle, whereas EFNA5 and RFTN1 are associated with meat color." (PMID 40520431, 2025). "Iroquois Homeobox 3 (IRX3), a highly conserved member of the Iroquois homeobox gene family, has been implicated in obesity through its regulation of fat mass and obesity-associated (FTO) gene." (PMID 41436436, 2025). "Variants near rs9939609 of the FTO gene are especially related to overall obesity and anthropometric traits like BMI and waist circumference." (PMID 40024983, 2025). "Another noteworthy target is fat mass and obesity‐associated (FTO), identified within the SOX2‐OT/MIR222HG/HOXA‐AS3/TUG1, and SOX2‐OT/MIR222HG/HOXA‐AS3/TUG1/CASC2 subnetworks." (PMID 40066229, 2025). "Changes in gene expression caused by demethylation of nucleic acids from the FTO protein can then increase the risk of obesity and other obesity-related diseases." (PMID 39981080, 2025). "The primary objective is to find the association of the FTO gene polymorphism rs9939609 with the risk of obesity and T2D in healthy young university students in Kuwait." (PMID 39925495, 2025). "Based on previous research, there is a relationship between polymorphisms of the FTO gene and obesity not only in Asian ethnic group but also in Caucasian and Hispanic." (PMID 39981080, 2025). "The common polymorphism rs9939609 of the fat mass and obesity gene (FTO) has been associated with increased susceptibility to obesity, but this association appears to be modified by diet." (PMID 41190148, 2025). "This is the case for the fat mass and obesity-associated (FTO) gene, one of the biggest genetic contributors to body mass index (BMI)." (PMID 41375608, 2025). "Unlike causal genes for monogenic obesity, such as MC4R or LEP, which have a direct role in early-onset and severe forms of obesity, FTO influences susceptibility through regulatory mechanisms." (PMID 40806129, 2025). "It is also noteworthy that a large number of publications focus on the protein FTO (fat mass and obesity-associated protein), which functions as an m6A RNA demethylase." (PMID 41303351, 2025).
Obesity (continued). "The FTO gene, which is associated with obesity, has been linked to various health conditions through its role in regulating body weight and metabolism." (PMID 40630163, 2025). "The fat mass- and obesity-associated (FTO) gene has primarily been studied for its role in regulating body mass and obesity, but recent research has begun to explore its broader impacts on metabolic diseases, including potential links to kidney disease." (PMID 41322097, 2025). "For instance, the fat mass and obesity gene (FTO) gene variation is found to be associated with genes predisposing to obesity, with increased fat accumulation in the body by influencing energy balance, appetite regulation, and metabolism." (PMID 41190148, 2025). "The role of fetal FTO risk variants in the regulation of maternal glucose metabolism during pregnancy and its subsequent contribution to obesity risk in adulthood needs to be further explored." (PMID 40877565, 2025). "Particularly, FTO is associated with body mass index (BMI) and obesity, which are known risk factors for OA and potentially for RA." (PMID 40943660, 2025). "The significance of this study is to understand the role of the FTO gene polymorphism to help determine the risk of obesity and T2D among the young people of Kuwait, who are subject to progressively increasing problems of obesity and diabetes." (PMID 39925495, 2025). "The most strongly associated with obesity and increased body mass index (BMI) is the first intron of FTO." (PMID 39981080, 2025). "While several studies have shown a strong association between FTO polymorphisms and obesity risk, only a limited number have investigated the genetic differences of FTO between MASLD." (PMID 40864759, 2025). "One example is the widely replicated obesity-associated variants around the FTO gene, for which multiple mechanisms and multiple gene targets have been proposed, with no clear consensus." (PMID 38849463, 2025). "Research has examined the association of the FTO gene with obesity, focusing on its role in metabolic regulation and energy balance." (PMID 40055285, 2025). "In humans, single nucleotide polymorphisms (SNPs) in the FTO gene are the strongest genetic link with obesity in genome‐wide association studies (GWAS)." (PMID 40022434, 2025). "IRX3 is linked to predisposition to obesity through the FTO locus and is upregulated during early adipogenesis in risk-allele carriers, shifting adipocyte fate toward fat storage." (PMID 40769964, 2025). "The FTO variant rs9939609 has been widely associated with obesity, but emerging evidence suggests a broader role for T2D risk across diverse populations." (PMID 41301409, 2025). "Genome-wide Association Studies have identified FTO as the first obesity-susceptibility gene in populations of European ancestry, resulting in its renaming as the “fat mass and obesity-associated” gene." (PMID 41141248, 2025). "‐Genetic predisposition with over 250 genes linked to obesity.‐FTO gene's role in obesity and type 2 diabetes.‐Cross‐sectional studies evaluating gene‐obesity links." (PMID 40551726, 2025). "FTO, an allele linked to obesity, is situated on the elongated segment of human chromosome 16, specifically 16q12.2." (PMID 39820532, 2025). "Although studies examining changes in PA in response to genetic risk disclosure for obesity have been conducted, existing research has predominantly focused on the FTO gene." (PMID 40423790, 2025). "The fat mass and obesity-associated protein (FTO) gene polymorphism rs9939609 is known to raise the risk of T2D through obesity." (PMID 39925495, 2025). "The fat mass and obesity associated (FTO) gene is one of the most prominent genetic variants linked to obesity, affecting energy homeostasis and associated with various metabolic disorders." (PMID 40428329, 2025). "Given the strong association of obesity with BC, several studies examined the relationship between FTO gene polymorphism and the incidence of BC." (PMID 40630163, 2025).
Obesity (continued). "Emerging evidence has highlighted the role of fat mass and FTO in the regulation of m6A RNA methylation, a process that influences gene expression and is implicated in both obesity and cancer." (PMID 40040878, 2025). "Numerous studies have demonstrated that polymorphisms within the fat‐mass and obesity‐associated gene FTO on chromosome 16 are associated with type 2 diabetes, most likely mediated through their effect on increasing BMI." (PMID 40538118, 2025). "Among all m6A-associated genes, FTO is renowned for promoting obesity, which is an important driving factor for HCC." (PMID 40316995, 2025). "FTO, the first identified m6A demethylase and an allele associated with obesity, possesses demethylase activity." (PMID 39820532, 2025). "This study aims to investigate the potential of electroacupuncture to mitigate myocardial ischemia–reperfusion injury (MIRI) by influencing N6-methyladenosine (m6A) methylation through modulation of the fat mass and obesity-associated protein (FTO)." (PMID 40918160, 2025). "Numerous genetic studies have revealed associations between specific polymorphisms and an elevated risk of obesity, including the rs9939609 SNP of FTO, which correlates with obesity and heightened adiponectin levels." (PMID 41423640, 2025). "Here, we identified that fat mass and obesity‐associated protein (FTO) serves as a protective factor against skin aging." (PMID 40636284, 2025). "In contrast, single-nucleotide polymorphisms (SNPs) in intron 1 of FTO are associated with an increased risk of obesity." (PMID 40429638, 2025). "Fat mass and obesity-associated (FTO) rs9939609 variants were significantly different among metabolic phenotypes of obesity." (PMID 40662170, 2025). "FTO and ALKBH5 are related by sequence and structure, and both are linked to cancer; mutations of the FTO gene are also linked to other diseases, including obesity and brain disorders." (PMID 40874592, 2025). "The levels of fat mass and obesity‐associated protein (FTO) and oxidative stress responsive 1 (OXSR1) were detected by quantitative real‐time PCR and western blot." (PMID 39739936, 2025). "In relation to obesity, the FTO variants (rs9939609 and rs8050136) and MC4R variants (rs17782313 and rs2229616) have been widely recognized for their roles in regulating appetite and energy balance." (PMID 40944253, 2025). "The fat mass and obesity-associated (FTO) variant rs9939609 has been linked to increased obesity and T2DM risk in Asian Indians, with its effect on T2DM partly mediated through BMI but highlighting unique adiposity patterns in this population." (PMID 41216008, 2025). "The cross-sectional study examined the relationship of the FTO rs9939609 gene polymorphism with obesity, BMI, and T2D in 201 apparently healthy young adults employed in the medical and dental fields." (PMID 39925495, 2025). "An important aspect of this study was the inclusion of genetic analysis, specifically the rs9939609 polymorphism of the FTO gene, which has been widely associated with obesity risk in different populations." (PMID 40349719, 2025). "Engaging in physical activity can reduce the effect of FTO SNPs on obesity susceptibility by approximately 30%, and evidence suggests that FTO influences food preferences and intake." (PMID 40564803, 2025). "This study investigated the effects of fat mass and obesity-associated (FTO) inhibition on cognitive function and metabolic parameters of senescence-accelerated mouse prone 8 (SAMP8) mice fed a high-fat diet (HFD)." (PMID 39984825, 2025). "Recent studies have demonstrated a complex association between polymorphisms in the FTO gene (fat mass and obesity-associated gene) and the risk of sarcopenia, influenced by population differences, varying diagnostic criteria, and environmental factors." (PMID 40428823, 2025).
Obesity (continued). "Obesity is a well-established risk factor for breast cancer (BC), with increasing evidence linking genetic factors, particularly the FTO gene, to obesity and BC susceptibility." (PMID 40630163, 2025). "The study investigated how the polymorphism of FTO rs9939609 gene is related to the obesity risk in children and adults in Asian countries." (PMID 39981080, 2025). "FTO is well‐recognised for its involvement in human adipogenesis and obesity and has further been associated with mitochondrial biogenesis and oxidative stress through post‐transcriptional modification of relevant genes." (PMID 40621649, 2025). "In human genetic studies, mutations in the FTO gene are strongly linked to obesity and diabetes; FTO polymorphisms are also implicated in attention-deficit/hyperactivity disorder, Alzheimer’s disease, and abnormal brain volumes." (PMID 40210977, 2025). "Modifications such as increased physical activity and specific dietary interventions have been shown to reduce FTO gene expression, potentially lowering obesity risk." (PMID 40630163, 2025). "This study specifically focuses on the FTO rs9939609 SNP, as its association with obesity and its role in BC risk, especially in populations with high rates of obesity, remains underexplored." (PMID 40630163, 2025). "Since the initial discovery of FTO variants in 2007, meta-analyses of large-scale GWAS have uncovered over 1000 loci, solidifying the understanding of common obesity." (PMID 40564803, 2025). "To elucidate the functional consequences of m6A modification, we subsequently generated m6A-deficient ALV-J through its culturing in the DF-1 overexpressing fat mass and obesity-associated protein (FTO) cells." (PMID 40198675, 2025). "Diverse genomic risk loci have been linked to diseases and traits, including PTPN22 for autoimmune disease and FTO (Fat mass and Obesity-associated) for obesity, according to a decade of GWAS." (PMID 39219434, 2025). "Studies have consistently shown that the A allele of the FTO rs9939609 variant is strongly linked to higher BMI and increased obesity risk." (PMID 40630163, 2025). "FTO is the first obesity susceptibility gene identified through GWAS and represents the locus with the greatest impact on body mass index and obesity risk." (PMID 40316995, 2025). "For example, the FTO locus, initially implicated in obesity risk by GWAS, has been extensively studied, with research elucidating the regulatory mechanisms involving ARID5B and its effects on IRX3 and IRX5 expression." (PMID 40564803, 2025). "Overexpression of FTO results in a body- and fat mass-dependent increase leading to obesity, whereas mice deficient in FTO show postnatal growth retardation and reduced food intake with a concomitant reduction in adipose tissue." (PMID 40662138, 2025). "Genetically, the Fat Mass and Obesity-Associated (FTO) gene and the Melanocortin-4 Receptor (MC4R) gene are recognized as contributors to polygenic and monogenic obesity, respectively." (PMID 41423640, 2025). "Two cancer-linked human Fe(II) and 2-oxoglutarate (2OG)-dependent oxygenases, the fat mass and obesity associated-protein (FTO), and AlkB human homolog 5 (ALKBH5) catalyse m6A methyl group oxidation." (PMID 40874592, 2025). "GWAS have shown that SNPs within FTO are significantly associated with obesity and cancer, while various investigations have highlighted the relationship between FTO's demethylase activity and cancer susceptibility at a molecular level." (PMID 40391584, 2025). "For example, the fat mass and obesity-associated (FTO) gene plays a critical role in determining an individual’s fat metabolism, a vital aspect of LCKD’s functionality." (PMID 40626223, 2025). "In this context, variants of the FTO gene (fat mass and obesity-associated gene) have gained considerable attention over recent decades due to their involvement in body weight regulation, adiposity, and insulin resistance, all factors closely linked to AD." (PMID 41303403, 2025).
Obesity (continued). "Meanwhile, FTO, a gene identified through genome-wide association studies (GWASs) as associated with obesity, plays a role in lipid accumulation by enhancing the maturation and nuclear translocation of SREBP1c." (PMID 40806129, 2025). "For instance, in the EPIC-Norfolk study of 20,000 adults, physically active individuals with high-risk FTO alleles had a 40% lower obesity prevalence compared to inactive carriers." (PMID 41302083, 2025). "The fat mass and obesity‐associated (FTO) gene, which is located on chromosome 16, is responsible for producing a nucleic acid demethylase enzyme that utilizes 2‐oxoglutarate and Fe(II) to catalyze the demethylation of 3‐methylthymine in single‐stranded DNA." (PMID 41324103, 2025). "Evidently, school-aged children with FTO risk alleles (rs9939609 A) had significantly higher obesity rates (OR = 2.45, p = 0.008), particularly in those with high-calorie diets and low physical activity." (PMID 40861630, 2025). "In a Mendelian randomization study of > 50,000 individuals of European ancestry, FTO polymorphism associated with obesity was significantly associated with an increased risk of incident AF." (PMID 41077815, 2025). "In this context, a recent investigation highlighted the racial differences in the methylation patterns of the nuclear respiratory factor 1 (NRF1), fat mass and obesity-associated (FTO), and leptin receptor (LEPR) genes among children with obesity." (PMID 40427561, 2025). "The fat mass and obesity-associated (FTO) rs9939609 T>A polymorphism is associated with excess body fat and metabolic disturbances, including Type 2 diabetes (T2D) and metabolic dysfunction-associated steatotic liver disease (MASLD)." (PMID 41141248, 2025). "While the FTO gene is particularly salient in obesity-related discussions, contemporary genome-wide association studies have elucidated its association with not just adiposity but also metabolic disturbances and, most concerningly, cancer." (PMID 40040878, 2025). "In this study, we identified a novel role for the obesity-associated protein FTO, which is known primarily for its function as an m6A eraser, in the pathogenesis of endometriosis." (PMID 40000966, 2025). "HFD-induced obesity in mice leads to increased FTO levels and loss of m6Am at specific targets such as Fabp2 and Fabp5 mRNAs." (PMID 40862085, 2025). "The rs9939609 polymorphism of the FTO gene has been widely associated with obesity in several European cohorts." (PMID 41190148, 2025). "FTO and IRX3, the prioritized genes of habitual snoring, were overrepresented in the FTO-obesity-variant-mechanism gene set (PFDR = 0.0005)." (PMID 38461358, 2024). "In contrast, it has been shown that for some FTO genotypes, a high-protein diet can reduce the risk of obesity and increase weight loss." (PMID 39458556, 2024). "While FTO has been previously associated with increased body mass and obesity in humans, a recent study demonstrated that cocaine CPP results in decreased levels of Fto in the mouse hippocampus." (PMID 38780720, 2024). "FTO gene variants have a strong association with obesity, metabolic syndrome, inflammation, hypertension, dyslipidemia, polycystic ovarian disease, and various cancers." (PMID 39257882, 2024). "The Fat mass and obesity-associated (FTO) gene is a key genetic predictor of obesity risk factors and is involved in the control of adipocyte differentiation." (PMID 39200098, 2024). "The FTO is a key gene identified through genome-wide association studies (GWAS) that contributes to polygenic obesity in people of diverse ethnic backgrounds, including both children and adults." (PMID 39224127, 2024). "The FTO rs9939609:T>A variant, located in intron 1, has been associated with obesity and increased risk of CVD." (PMID 38610209, 2024).